NRP1 (neuropilin 1)
Diseases named in the same sentence as NRP1 in open-access papers (continued):
Sharing a sentence is not in itself a finding about the gene and the disease.
tumor (continued). "Meanwhile, NRP1 was recently shown to have an immune suppressive role in CD4+ T cells and regulatory T cells in immune diseases and tumor immunity." (PMID 38994453, 2024). "Upon binding, iRGD undergoes proteolytic cleavage to expose the CendR motif, which interacts with neuropilin-1 (NRP-1) receptors, facilitating deep tissue penetration and enhanced drug delivery into the tumor parenchyma." (PMID 39411070, 2024). "Although NRP1 and NRP2 also affect myoepithelial cell tumor suppressor function, cells presence and integrity are disturbed, clearly disrupting the basal membrane structure." (PMID 39138514, 2024). "In breast cancer, one such cell population is characterized by several molecular markers (CD44 positive, NRP1 high, ALDH1 positive, and CD24 low) and is often referred to as the cancer stem-like cell (CSC) population or tumor-initiating cells." (PMID 39420119, 2024). "Meanwhile, PEI-elastase facilitated PD-L1siRNA entry into tumor cells via NRP1-mediated transcytosis and PEI-mediated endocytosis, and then reduced tumor PD-L1 expression." (PMID 39068444, 2024). "We further identify NRP1 and ITGB1 as pivotal functional receptors of Sema3C, activating downstream AKT/Gli1/c-Myc signaling pathways to bolster HCC self-renewal and tumor initiation." (PMID 38956074, 2024). "Regarding the NRP1/PKC pathway, inhibition of NRP1 protein expression or suppression of PKC activation leads to the inhibition of NE differentiation and prevents tumor progression towards castration resistance." (PMID 37761978, 2023). "As a transmembrane glycoprotein receptor, NRP consists of two members, NRP-1 and neuropilin-2 (NRP-2), which regulate neurogenesis, angiogenesis, vascular permeability, and immune response, as well as tumor growth and vascularization." (PMID 36903540, 2023). "Thyroid tissues were immunohistochemically stained for different tumor proliferative markers: Minichromosome maintenance proteins 2 (MCM2), Ki-67 labeling index, E-Cadherin, Neuropilin-1 and Metallothionein." (PMID 36676734, 2023). "Blockage of the Sema3A/NRP1 axis via shRNA-mediated knockdown of Sema3A or NRP1 impeded clonogenic growth and TGF-β pathway activity in GSCs and inhibited tumor growth in vivo." (PMID 37788099, 2023). "Interestingly, a higher molecular weight-modified NRP1 (mNRP1) type was identified in a large proportion of oesophageal SCC tumors, and its expression is associated with less lymph node metastasis and a better prognostic tumor–node–metastasis stage compared to mNRP1-negative tumors." (PMID 37894289, 2023). "NRP1 intrinsically regulates both Treg cell and CD8+ T‐cell functions to collectively impede antitumor immunity in the tumor microenvironment." (PMID 35621244, 2023). "In particular, the expression of neuropilin-1, VEGF, and VEGFR2 in tumor cells remained unchanged (unchanged auto- and paracrine VEGF tumor cell signaling), independently of the therapeutic modality (at least under the conditions applied in this study)." (PMID 38201461, 2023). "The cleavage form of iRGD binds to NRP-1 and subsequently triggers NRP-1 dependent endocytosis, thereby enhancing tumour infiltration." (PMID 37764308, 2023). "There is substantial evidence to show that the efficacy of CTX is related to its ability to cross the BBB as well as its high tumor-binding function mediated by the molecular targets namely, chloride channels, MMP-2, annexin A2, and recently, ERα and NRP-1." (PMID 37444498, 2023). "Furthermore, HIF1α directly regulates NRP1 expression in cells exposed to a hypoxic microenvironment, suggesting a role for HIF1α-induced hypoxic responses in promoting lenvatinib resistance, particularly when the silencing of HIF1α enhances the anti-tumor effects of lenvatinib." (PMID 36769116, 2023).
tumor (continued). "We found that in the PTEN low-expression group, there was a significant decrease in the expression of some immune checkpoints, including CD276, CD274, NRP1, and the TNFRSF family, that are closely involved in immunosuppressive signals in HCC tumor." (PMID 36861063, 2023). "The tumor penetrating peptide iRGD synthesized by combining RGD with CendR motif not only binds to integrins αvβ3 and αvβ5, but also neuropilin-1 (NRP-1)." (PMID 36762192, 2023). "The selected targets were patient-specific, as the analysis of another individual’s HPV+ OPSCC, showed that although some interactions, such as VEGFA/NRP1 and VEGFA/GPC1 were present, the most active L-Rs in the tumor were VEGFA/NRP2 and EGFR-related pathways." (PMID 37704757, 2023). "Tumor size-related proteins were involved in angiogenesis (VCAN, VTN, NRP1), EMT (FN1, CD44, THBS2), and translation (EIF1AX, EIF5), further indicating the biological basis of ccRCC growth." (PMID 37460463, 2023). "Through various tumor-specific analyses, we show that PRV-LAV infects cancer cells via the NRP1/EGFR signaling pathway, which is commonly overexpressed in cancer." (PMID 37891570, 2023). "Analysing the results of the uptake inhibition studies, comparable iNGR and NGR concentrations were found in the HT1080 tumours post application of a neutralising NRP-1 antibody, which strengthens the role of NRP-1 in the internalization of iNGR." (PMID 37628856, 2023). "Another research group identified neuropilin 1 (NRP1), an endocytic receptor on tumor and endothelial cells, as a novel CTX target." (PMID 37394009, 2023). "VEGFs have their own specific receptors (VEGFRs) but can also bind to NRP-1 and NRP-2 and have a well-established role in tumour growth by promoting neovascularisation, which is essential for the survival of the growing tumour mass." (PMID 37685898, 2023). "Our results also showed that the expression of NRP1 and NRP2 was positively correlated with the infiltration of CAF, which can interact with tumor cells, promote tumor growth and maintain malignant tendency." (PMID 37190154, 2023). "Downmodulation of either NRP1 protein expression or PKC activation suppresses NED, prevents tumour evolution toward castration resistance and increases the efficacy of docetaxel-based chemotherapy in preclinical models in vivo." (PMID 36550208, 2023). "Our examination of the human SU2C-PCF CRPC dataset revealed that NRP1 and downstream PKC players are expressed in a subset of NEPC tumours." (PMID 36550208, 2023). "Overexpression of miR-124-3p inhibits GBM cell proliferation, migration, and tumor angiogenesis, resulting in GBM apoptosis and cell cycle arrest through NRP1 mediated activation of the phosphoinositide 3 kinase (PI3K)/Akt/NFκB pathway." (PMID 37894289, 2023). "In TIGIT+ Treg cells, the expression level of many immunosuppressing marker genes, including Foxp3, Helios, neuropilin-1, CTLA-4, PD-1 and LAG-3, was upregulated, which inhibited the tumor killing function of T cells." (PMID 38110467, 2023). "NRP1 has been shown to be highly expressed in NSCLC is believed to correspond to poor patient prognosis, it is therefore a potential target for tumor therapy." (PMID 36994202, 2023). "For example, the NRP1-specific small-molecule inhibitors EG00229 and ATWLPPR have been demonstrated to inhibit NRP1-VEGFR-2 signaling, and impair both tumor angiogenesis and tumor growth in vivo." (PMID 36970722, 2022). "Solid tumor development is aided when NRP-1 binds VEGF-A, while SEMA3A binding often improves prognosis by limiting tumor cell motility and invasion." (PMID 35052853, 2022). "These experiments indicate that the Nrp1-VEGF axis contributes to cancer cell stemness and tumor initiation." (PMID 36203599, 2022). "miR-320 negatively regulated the expression of NRP-1 by binding to the 3’-UTR of the NRP-1 promoter, thereby promoting tumor angiogenesis." (PMID 36011390, 2022).
tumor (continued). "The research results of this project suggest that the present ChIP-seq and RNA-seq analyses reveal that NRP1 is a key gene directly regulated by GATA3 and H3K4me3 that is involved in the formation of tumor cell radiation resistance." (PMID 35993027, 2022). "Sema3A binds to the neuropilin 1 (NRP1) receptor, ultimately inhibiting tumor growth and angiogenesis." (PMID 36499024, 2022). "NRP1 is a marker for CD4+ regulatory T cells, is sometimes coexpressed with PD-1 on a subset of CD8 tumor-infiltrating T lymphocytes, and inhibits T cell antitumor immunity." (PMID 36131795, 2022). "BTICs also express NRP1 which increases BTIC marker expression, neurosphere formation capacity, migration, and tumor growth." (PMID 36345944, 2022). "Through qRT-PCR on clinical samples, expression of NRP1, IGF2R, SERPINA3 and TNF were significantly upregulated in tumor tissue, while ICOS and DES were significantly downregulated." (PMID 36406134, 2022). "NRP1 is an independent novel marker in RCC, which forms a complex with transexpressed VEGFR2 and inhibits tumor angiogenesis, thereby improving patient survival." (PMID 35686121, 2022). "Consistently, the depletion of NRP-1 from microglia in glioma-bearing mice leads to a reduction in GBM volume, increasing the number of T CD8+ cells in the tumor mass and shaping GAM polarization." (PMID 35681612, 2022). "We also showed that probes ICAM1, calreticulin, PD-L1, neuropilin-1, galectin-3 and MPO were spatially associated with immunogenic cell death and, together with the enriched standard cell types, they might serve as an early predictive biomarker of induced anti-tumor immunity in situ." (PMID 35788566, 2022). "Probing the role of VEGF further, the group overexpressed VEGF while knocking out Nrp1; the results indicated tumor epithelial cells overexpressing VEGF resulted in accelerated tumor growth." (PMID 36203599, 2022). "According to the qRT-PCR results, expression levels of NRP1, IGF2R, SERPINA3 and TNF were significantly upregulated in the comparison between in situ tumor samples and normal tissues in our clinical center." (PMID 36406134, 2022). "An anti-NRP1 antibody, in combination with an anti-PD-1 antibody, has been shown to improve CD8 T-cell proliferation, cytotoxicity, and tumor control." (PMID 35794981, 2022). "We provided evidence that Neuropilin-1, highly expressed by Tregs, regulates the migration of Tregs into VEGF-producing tumor tissue accompanied by elevated tumor progression." (PMID 36426850, 2022). "Moreover, a preclinical study employed NRP1 knockdown human hepatoma cells to generate a mouse model of HCC, observing that NRP1 loss reduced the tumor volume when compared to non-transfected hepatoma cells, providing evidence of the role of NRP1 in tumor development and pathogenesis." (PMID 35884516, 2022). "Further analysis showed that hypoxia-induced immune checkpoints, such as CD276 and NRP1, upregulation in invasive tumor to block infiltration and activation of B cells and CD8+ T cells to change tumor immune microenvironment." (PMID 36685583, 2022). "A marker used to describe cancer cells stemness is CD34: Nrp1 was expressed the highest in CD34+ cells when compared to normal interfollicular keratocytes, hair follicle bulge stem cells, and CD34- tumor epithelial cells." (PMID 36203599, 2022). "The neuropilin (NRP) family is comprised of two genes, neuropilin-1 (NRP-1) and neuropilin-2 (NRP-2), and participate in a variety of signaling pathways that contribute to the cytoskeletal structure, angiogenesis, and tumor development." (PMID 35052853, 2022). "Fourteen isoforms of NRP1 were differentially expressed in tumor tissues, Usage of the isoform ENST00000374875.5 (NRP1-002) was the highest among all the isoforms, followed by the isoform ENST00000374867.6 (NRP1−202)." (PMID 36338984, 2022).
tumor (continued). "In untreated CT-26 tumor-bearing animals, there was a notable increase in the density of tSNE regions that mapped to the expression of FoxP3, CD25, TGF-β, and NRP-1." (PMID 36090972, 2022). "Comparisons between two SARS-CoV-2 receptors, NRP1 and ACE2, in 23 different tumor and matched normal tissues were conducted using the TCGA dataset in GEPIA2." (PMID 36338984, 2022). "Here we demonstrate, using NRP1ECKO, NRP2ECKO, and NRP1/NRP2ECKO mouse models, that maximum inhibition of primary tumor development and angiogenesis is achieved when both endothelial NRP1 and NRP2 are targeted simultaneously." (PMID 36970722, 2022). "The overexpression of some certain ARGs, such as vascular endothelial growth factor A (VEGFA), neuropilin-1 (NRP1) and PlexinA2 (PLXNA2), were found in PCa and their overexpression correlated with tumor metastasis and poorer prognosis." (PMID 35836112, 2022). "The overexpression of the neuropilin-1 (Nrp1 in mice and NRP1 in humans) in GBM has been shown to support tumor cell growth, metastasis, and immune evasion." (PMID 36311702, 2022). "GEPIA2 was used to analyze NRP1 (ENSG00000099250.17) isoform prevalence and structure in 33 tumor types." (PMID 36338984, 2022). "Our results highlight the importance of targeting both NRP1 and NRP2 to modulate tumor angiogenesis." (PMID 36970722, 2022). "In tumor-bearing animals, the expression of Nrp-1 behaves similarly as in naive draining lymph nodes on cTreg and Tr1 cells, but PD-1 and CD73 show opposite trends within the tumor versus naive (or TdLN)." (PMID 35860556, 2022). "Overall, it was validated that miR-378c inhibited tumor growth and lung metastasis of STAD in vivo through mediating NORAD/NRP1 axis." (PMID 35164743, 2022). "In humans, the NRP-1/VEGF-A complex has been extensively studied in cancer, due to its role in tumor progression and invasiveness." (PMID 36557705, 2022). "Meanwhile, we show the IHC staining of NRP1, HAVCR2, HHLA2CD44, TNFRSF18, TNFSF14, TNFRSF8, and CD276 in tumor tissues and normal tissues." (PMID 35685438, 2022). "The hydrophilic cyclic peptide iRGD is located on the outer surface of the NT, and not only improves the solubility of the hydrogelator, but also has the ability to target the tumor via binding neuropilin-1 and enhancing CPT’s tumor penetration ability." (PMID 35057106, 2022). "Analysis of Kaede Red+ Tregs within the dLN after photoconversion of the tumor revealed that the majority were NRP-1+ LAG-3− (the “Treg1” phenotype), although a minor NRP-1− LAG-3− population was also detected." (PMID 35472220, 2022). "It has been reported that the NRP1 promoter can directly bind to HIF-1α, which is a critical tumor driver involved in PI3K/AKT regulation and can facilitate the upregulation of both HIF-1α and PI3K/AKT through a positive feedback loop." (PMID 35281516, 2022). "In our previous report, we subcloned the radiation-surviving tumor cells (IR cells) using the human NSCLC cell line, H1299, and found that the expression of neuropilin-1 (NRP-1) was upregulated in IR cells by the microarray analysis." (PMID 34698100, 2021). "A recent study revealed that neuropilin-1 (NRP-1) expression is significantly upregulated in hypoxic areas and induces pro-tumor phenotypes in recruited macrophages." (PMID 34603327, 2021). "We found that AMPK-KO Tregs expressed higher levels of PD-1, Nrp1, and ICOS than Tregs from WT mice in both tumor-free and tumor-bearing mice." (PMID 34649584, 2021). "A F-18 labeled construct targeting αvβ3 and NRP-1 via an RGD-ATWLPPR heterodimer showed higher uptake and tumor-to-background ratios in a glioblastoma model than the respective monomers." (PMID 33916607, 2021). "Statistical results showed that the level of NRP1 in GC was significantly related to tumor size, TNM stage, depth of tumor invasion, N stage, and distant metastasis (P<0.001), but was not significantly related to other clinicopathologic factors." (PMID 33995640, 2021).
tumor (continued). "NRP1 also acts as a receptor for the class 3 semaphorin (SEMA3A) to regulate vascular permeability and vessel maturation during tumor angiogenesis." (PMID 33850110, 2021). "Immune checkpoint molecules, such as CTLA4, NRP1, TNFSF15, CD44, and BTLA, are present in the TME or on the surface of tumor cells, and they negatively regulate T cell activation." (PMID 34926701, 2021). "Although NRPa-308 represents an interesting hit if tumor cells express both NRPs and their ligands VEGFA/VEGFC, specific drugs targeting NRP1 should be more appropriate if only NRP1/VEGFA is present." (PMID 33461580, 2021). "Compared with normal tissues, NRP1 and TMPRSS2 promoters in LUAD and LUSC both show increased methylation, consistent with the decreased NRP1 and TMPRSS2 expression in tumor tissues." (PMID 34168096, 2021). "In NSCLC, it was described as a tumor suppressor acting on insulin growth factor (IGF)-1R53, being involved in tumor growth and metastasis through STAT3 and Neuropilin 1 downregulation." (PMID 33451052, 2021). "Correlation analysis of protein levels of VEGF-A with the receptors VEGFR-1 -3 and with the co-receptor NRP-1 showed a significant correlation between VEGF-A and VEGFR-1 on tumor cells and tumor vessels (p < 0.0001)." (PMID 33528717, 2021). "In summary, Tregs support pro-tumor angiogenesis in the TME via secretion of VEGF-A and IL-10, and expression of NRP1." (PMID 34177968, 2021). "Recently, we reported the identification and characterization of a panel of homing peptides that target tumor ECM: a peptide that binds to TNC-C and Fn-EDB (PL1 peptide), to Fn-EDB and neuropilin-1 (NRP-1) (PL2 peptide), and to TNC-C and NRP-1 (PL3 peptide)." (PMID 34947606, 2021). "Most recently, the vascular endothelial growth factor (VEGF) receptor, Neuropilin-1 (NRP1) was identified as the likely receptor, responsible for tumour uptake." (PMID 34401749, 2021). "Pharmacological inhibition of BRD4 decreased NRP1 expression and ablated FGF-mediated tumor cell growth." (PMID 33128042, 2021). "Overexpression of both, NRP1 and NRP2 was reported in non-small cell lung carcinoma and it significantly correlated with tumor progression." (PMID 34961486, 2021). "miR-148b significantly inhibits tumorigenicity in vivo, possibly due to its target neuropilin-1 (NRP1), which is involved in tumor initiation, metastasis and angiogenesis." (PMID 34659567, 2021). "Strikingly, a NRP1 antagonist increased CD8+ T cell infiltration and decreased tumor growth in a murine model." (PMID 34177968, 2021). "Both NRP1 and TMPRSS2 are decreased in tumor tissues of LUAD and LUSC compared with paired normal tissues." (PMID 34168096, 2021). "In the present study, we focused on neuropilin-1 (NRP-1) among the upregulated genes in the IR cells that survived 10 Gy of X-ray irradiation, that was 2.4-fold upregulated than the original tumor cells in microarray analysis." (PMID 34698100, 2021). "The expression of both NRP1 and NRP2 was found in many tumor types, where their overexpression contributed to metastasis." (PMID 35008571, 2021). "HIF-1α/NRP1 signaling can subsequently result in activation of MMP2, Vimentin, and VE-cadherin and thus promote EMT and VM, which ultimately contribute to tumor progression in LUAD." (PMID 33850110, 2021). "The MCT1KO Treg cells that present a reduced suppressive function ex vivo, decreased expression of Nrp-1 and elevated PD-1 levels lost their suppressive function and allowed the control of B16F10 tumor growth." (PMID 34539668, 2021). "High LPAR6 expression relates to a high infiltration level of DCs in the tumor tissue of LUAD patients, DC markers such as HLA-DQB1, CD1C and NRP1 show significant correlations with LPAR6 expression both in the tumor tissue in LUAD." (PMID 34769557, 2021). "The results of the prognostic model on HCC prognosis and chemosensitivity as constructed using BACE1-AS and NRP1 further confirm the close relationship between BACE1-AS and tumor immunity in tumor progression." (PMID 34926701, 2021).